C3 (complement C3)
Diseases named in the same sentence as C3 in open-access papers (continued):
Sharing a sentence is not in itself a finding about the gene and the disease.
lupus nephritis (121 papers, 2009 to 2026). Glomerulonephritis in the context of systemic lupus erythematosus. "All cases were positive for ANA and anti-dsDNA antibodies, confirming their diagnostic utility in pediatric lupus nephritis, while reduced serum complement (C3 and C4) levels were observed in 86.3% of patients, comparable to previous findings." (PMID 41426831, 2025). "In our study, low C4 levels were significantly associated with an increased risk of AIHA, whereas low C3 levels were linked to the presence of lupus nephritis." (PMID 41156173, 2025). "Low C4 was associated with increased autoimmune hemolytic anemia risk (OR 5.88, p = 0.009), while low C3 was linked to lupus nephritis (p = 0.017)." (PMID 41156173, 2025). "Collectively, these findings demonstrated that Ferrostatin-1 improved renal damage caused by lupus nephritis through multiple mechanisms: reducing cell apoptosis, inhibiting inflammatory responses, alleviating fibrosis, and mitigating C3 deposition." (PMID 39500879, 2024). "Fundamentally, this is in line with previously published reports that described SLE flares to be frequently associated with decreased levels of complement C3 and C4, while anti-dsDNA concentrations increased, particularly in lupus nephritis." (PMID 38130723, 2023). "According to the literature, IgG anti-dsDNA autoantibodies titres and low complement C3/C4 are associated with lupus nephritis and recurrent disease flares." (PMID 36835833, 2023). "Genetic analysis have shown complement C3 gene mutations, which hints the co-existence of lupus nephritis with aHUS, a form of complement-mediated TMA." (PMID 33691638, 2021). "In this report, we describe a patient diagnosed with concurrent C3 mutation-related aHUS and lupus nephritis who was successfully treated with eculizumab." (PMID 33691638, 2021). "The present study showed for the first time that a pre-pregnancy serum C3 level < 85 mg/dl, in addition to a history of lupus nephritis, is a risk factor for preterm birth." (PMID 33980284, 2021). "The presence of C3 mutation and incomplete response to conventional immunosuppression are consistent with diagnosis of co-existent lupus nephritis and aHUS (complement-mediated TMA)." (PMID 33691638, 2021). "The deposition of IgG and C3 in the glomeruli is one of the prominent features of lupus nephritis and is the principal underlying cause for kidney damage in MRL-Fas/Lpr mice." (PMID 29358664, 2018). "Certain studies have shown that glomerular C3 deposition is associated with the disease activity and the severity of kidney injury in IgAN and lupus nephritis (LN)." (PMID 30003098, 2018). "In the present study, the favorable effects of BPs treatment on markers of active lupus nephritis were associated with a significant reduction of complement C3 in kidney, a marker of intraglomerular complement activation." (PMID 22701502, 2012). "Hypocomplementemia, specifically low C4 levels, was associated with an increased risk of autoimmune hemolytic anemia (OR = 5.88, 95% CI: 1.57–22.04, p = 0.009), whereas reduced C3 levels were significantly associated with the presence of lupus nephritis (p = 0.017)." (PMID 41156173, 2025). "C3 deposition is a hallmark of immune complex-mediated kidney damage in lupus nephritis." (PMID 39500879, 2024). "In addition, 24-hour proteinuria showed good diagnostic value in identifying nephritis in SLE patients (AUC=0.94), whereas anti-dsDNA, complement C3 and C4 have limited diagnostic value in lupus nephritis." (PMID 36845141, 2023). "Complement involvement in SLE pathogenesis is suggested by the association with inherited complement defects, reduced circulating complement levels in active disease, glomerular C3 deposits in lupus nephritis, genome-wide association studies, animal models, and the finding of retinal drusen." (PMID 35497809, 2022).
lupus nephritis (continued). "Candidate risk factors obtained from the results of univariate analysis comparisons between the two groups included age at pregnancy, which is commonly cited as a risk of preterm birth, history of lupus nephritis, past use of GC pulse therapy, and serum C3 level < 85 mg/dl." (PMID 33980284, 2021). "After controlling for age, level of immune suppression, and lupus nephritis diagnosis, logistic regression showed that patients with a low C3 measurement have a significantly higher risk of infection than those with a normal C3 level (OR 5.34 [95% CI, 1.88–15.16])." (PMID 32972440, 2020). "Activation of the alternative pathway, seems essential too, given that more C3 than C4 deposits, that deficiencies of factors of the alternative pathway, like FB and FD, ameliorate lupus nephritis, and that deficiencies of its inhibitory factors, like FH, promote lupus nephritis in animal models." (PMID 33643288, 2020). "Pediatric patients with severe C3 consumption represent a population with significant infectious risk comparable to that of patients with primary complement deficiency, even while adjusting for immunosuppression level and lupus nephritis diagnosis." (PMID 32972440, 2020). "However, we found that the phenomenon of NLRC5 in IgAN is similar to C3 complement in kidney diseases such as lupus nephritis, in which it was reported that C3 is associated with the activity and deterioration of lupus nephritis." (PMID 30453994, 2018). "Notably, the association between FHR-5 and C3 was also observed in membranous nephropathy, lupus nephritis, and postinfectious nephritis, indicating that this phenomenon is not specific to IgAN." (PMID 28673452, 2017). "Indeed, their data suggested that C3 levels and anti-dsDNA titers correlated with the severity of the lupus nephritis at presentation, while anti-dsDNA titers was associated with the severity of the histopathological changes." (PMID 23876025, 2013). "Moreover, high titers were preferentially associated with active lupus nephritis class IV, casts, hematuria, proteinuria, leukocyturia, leukocytopenia, monocytopenia and consumption of C3." (PMID 21329504, 2011). "Thus, the occurrence of lupus nephritis is associated with higher autoimmune profile, indicated by higher anti-double-stranded deoxyribonucleic acid antibodies (anti-dsDNA) and greater consumption of complement indicated by low C3." (PMID 37719585, 2023). "C3 GP must be differentiated from other types of glomerulonephritides that have excessive activation of the C system in the presence of circulating immune complexes, causing postinfection glomerulonephritis or secondary glomerulonephritides (lupus nephritis, essential cryoglobulinemia, and others)." (PMID 31947692, 2020). "We have previously reported cross-sectional associations between higher NfL levels and factors linked to a higher SLE disease burden, such as organ damage (SDI), low complement C3, anti-dsDNA antibodies, and lupus nephritis." (PMID 40114276, 2025). "Positive antinuclear antibody (ANA) tests, elevated anti-dsDNA levels, and low complement C3 are critical indicators of SLE, with anti-dsDNA strongly associated with disease activity and lupus nephritis." (PMID 40718534, 2025). "Our patient tested positive for ANA, p-ANCA, anti-SSA and had low C3 with elevated inflammatory markers and biopsy proven Class IV lupus nephritis." (PMID 39661284, 2025). "Significant complement consumption (C3 and C4) was observed in patients with lupus nephritis (35% of all cases)." (PMID 41327135, 2025). "Lupus nephritis, preeclampsia, C3, C4 complement components, hypertension, anti-Ro, anti-La, aPL antibodies, SLE flares, age, disease activity, duration, and IV cyclo-therapy were evaluated as potential predictors." (PMID 40981172, 2025).
lupus nephritis (continued). "Based on univariate analysis, SLE duration at conception, lupus nephritis (LN), history of therapeutic abortion, C3, lupus anticoagulant, IgG, serum ALB, CRP, PRO, HDL, and HCQ levels were significantly associated with the occurrence of fetal loss." (PMID 39044159, 2024). "Given the known role of the classical complement pathway activation in lupus nephritis, some have investigated urinary markers C3d, a degradation product of C3, as a potential marker of classical pathway activation and lupus nephritis disease activity." (PMID 38895123, 2024). "Histopathologic assessment revealed proliferation of mesangial cells, with deposition of IgG and complement components C3 and C1q (all characteristic features of lupus nephritis) in the glomerulus of 7-month-old HOIL-1LΔRING1/ΔRING1 female mice." (PMID 38329126, 2024). "Patients with lupus nephritis also exhibit decreased serum C3 complement levels, which can return to normal after remission." (PMID 39087011, 2024). "In our case, the patient's elevated anti‐dsDNA, low complement levels (C3 and C4), and the presence of lupus nephritis align with these pathophysiological mechanisms." (PMID 39582728, 2024). "On Direct Immunofluorescence (DIF), Lupus nephritis showed full house positivity in almost all cases with maximum positivity in Ig G (82.14%) followed by C3 (78.57%) and C1q (75%) respectively." (PMID 36301960, 2022). "C4d and C3 depositions are surrogate markers of complement activation, especially C4d for AMR and C3 for lupus nephritis, including in the TC model for the latter." (PMID 35860280, 2022). "On DIF, Lupus nephritis showed full house positive in almost all cases with maximum positivity in Ig G (82.14%) followed by C3 (78.57%) and C1q (75%) respectively." (PMID 36301960, 2022). "Multivariate analysis identified history of lupus nephritis (odds ratio: 5.734, 95% CI 1.568–21.010, P = 0.008) and low C3 level (< 85 mg/dl) at pre-pregnancy (odds ratio 4.498, 95% CI 1.296–15.616, P = 0.018) as risk factors for preterm birth." (PMID 33980284, 2021). "The multivariate analysis using these variables identified a history of lupus nephritis (OR 6.267, 95% CI 1.750–22.443, P = 0.005) and pre-pregnancy serum C3 level < 85 mg/dl (OR 4.754, 95% CI 1.373–16.461, P = 0.014) as the risk factors for preterm birth." (PMID 33980284, 2021). "Niclosamide treatment greatly improved proteinuria, anti-dsDNA antibody levels, immunoglobulin subclass titers, histology of lupus nephritis, and C3 deposition in MRL/lpr and R848-induced mice." (PMID 33632240, 2021). "We compared the serum C3 levels and history of lupus nephritis between the spontaneous delivery group (n = 50) and caesarean section group (n = 33)." (PMID 33980284, 2021). "There is a wide current development of blocking agents against different components of complement such as APL-2 (pegcetacoplan derivative of compstatin that blocks C3) or narsoplimab (that blocks MASP2) in lupus nephritis, and IFX-1 (that blocks C5a) in AAV." (PMID 33451011, 2021). "Isolating lupus nephritis patients, the C3 level at the beginning of observation trended lower in those with SBI compared to those without (P = 0.139)." (PMID 32972440, 2020). "IgA, IgG, IgM, C3, and C1q deposits by immunofluorescence were simultaneous detected in all the 26 ANCA positive patients, indicating lupus nephritis instead of ANCA associated vasculitis." (PMID 33604317, 2020). "Positive ANA and anti-ds-DNA antibodies, low C3 protein, lupus nephritis class III, acute cutaneous manifestations, seizures, and the evident fluid accumulation all sum up to 35 points on the 2019 EULAR/ACR criteria." (PMID 33143705, 2020). "Assessment of renal biopsy specimens at second admission demonstrated membranoproliferative glomerulonephritis via light microscopy and positive stains for IgG, IgM, IgA, C3, and C1q in immunofluorescence studies, compatible with class IV + V lupus nephritis." (PMID 31399881, 2019).
lupus nephritis (continued). "The complement C3 level tends to be higher in the milder lupus nephritis than the severe proliferative nephritis." (PMID 31842967, 2019). "Other authors reported that approximately 30% of patients with lupus nephritis were positive for anti-C3 autoantibodies." (PMID 31068950, 2019). "This is because the presence of autoantibodies is a requirement for the development of lupus nephritis, and deposition of complement proteins including the CP components C1q, C4, and C3 in the glomeruli are key features of lupus nephritis." (PMID 29892304, 2018). "Correlation coefficients between reactivity with modified and unmodified histone peptides, dsDNA, chromatin or histones, and disease activity (SLEDAI) or complement C3 levels in SLE patients with lupus nephritis." (PMID 27780265, 2016). "As expected, SLEDAI or daily urinary protein levels were significantly increased and serum C3 levels were significantly decreased in active lupus nephritis patients compared to those in inactive lupus nephritis patients." (PMID 27557500, 2016). "In patients with lupus nephritis the plasma levels for complement C3 and C4 are decreased due to renal complement deposition." (PMID 27091114, 2016). "JKAP protein level in T cells was the only variate that significantly correlated with the active lupus nephritis after comparison with serum levels of dsDNA, C3, and C4 (n = 43, odds ratio = 0.000028, P = 0.029)." (PMID 27557500, 2016). "We present a patient who suffered two lupus nephritis episodes in 5 years, achieving complete remission with treatment after both of them, but with C3 levels persistently below normal range." (PMID 25886501, 2015). "Together with dsDNA antibodies, low C3 and C4 are also biomarkers of lupus nephritis, but low C3 levels seem to be more sensitive than low C4 levels to diagnose renal SLE flares." (PMID 26583157, 2015). "Patients with active lupus nephritis had significantly lower levels of C3 and C4 compared to patients with inactive lupus nephritis." (PMID 23557013, 2013). "Serum C3 has generally higher sensitivity than serum C4, but both tests have only modest specificity for active lupus nephritis." (PMID 23557013, 2013). "Pegcetacoplan (APL-2), a C3 and C3b inhibitor, has been evaluated in a phase II clinical trial as a treatment option for IgAN, lupus nephritis, primary membranous nephropathy (MN), and C3 glomerulopathy (ClinicalTrials.gov Identifier: NCT03453619), however, no data are available at this time." (PMID 38398259, 2024). "In lupus nephritis, low serum C3 levels at diagnosis or at the time of remission may predict renal flares." (PMID 36830735, 2023). "Additionally, fluctuations in C3 and C4 levels were also demonstrated to be predictive for lupus nephritis." (PMID 37719585, 2023). "Silencing HE4 improved renal fibrosis and inhibited inflammation in mice with lupus nephritis, which may play a role in inhibiting C3/MMPs and promoting prss-related protein expression." (PMID 38157023, 2023). "Several investigators reported that the complement split products like C3 fragment, C4d, C5a and C5b-9 could be detected in the urine of lupus nephritis (LN) patients, and found that the levels of C3d in urine was closely related to LN disease activity." (PMID 36420131, 2022). "The "full-house" immunofluorescence pattern is characterized by the presence of IgG, IgM, and IgA, and C3 and C1q deposits, which occurs mostly in lupus nephritis (71%), with a sensitivity of 71%, specificity of 90%, positive predictive value of 79%, and negative predictive value of 85%28." (PMID 33501927, 2022). "Complement and Ig deposition in involved tissues and cells of SLE patients such as collocation of IgG, IgA, and IgM with C1q, C4, and C3 factors (and C5b-9; the so-called “full house” pattern) in the glomeruli is almost exclusively present in patients with lupus nephritis." (PMID 33451011, 2021).
lupus nephritis (continued). "In vehicle- or TAC-treated lupus nephritis mice, mild mesangial and subendothelial immune depositions of complement factors (C3 and C1q, as well as fibrinogen, IgG, IgA, and IgM) were detected, whereas the kidneys of HGC-TAC treated MRL/lpr mice displayed decreased immune deposits." (PMID 33865397, 2021). "The so-called “full-house” immunofluorescent staining pattern carried out as the gold-standard clinical testing in lupus nephritis biopsies with colocalization of IgG, IgM, IgA, C1q, and C3 (C4) is almost solely seen in lupus nephritis in contrast to other glomerular kidney diseases." (PMID 33864499, 2021). "The association between full house immunostaining (staining for all immune reactants, IgG/IgA/IgM/C1q/C3) and membranoproliferative, mesangioproliferative or membranous pattern is highly suggestive for lupus nephritis, which explains why some authors consider HUVS as a SLE-related syndrome." (PMID 32640739, 2020). "Serum complements (C3 and C4) correlate with lupus nephritis, but they do not associate with total disease activity as well as SLE non-renal activity." (PMID 31842967, 2019). "Notably, the diagnostic power of JKAP downregulation in T cells for active lupus nephritis was higher than those of serum anti-dsDNA antibody, C3, and C4 levels." (PMID 27557500, 2016). "However, only T cell Gαq mRNA expression was negatively correlated with SLEDAI, urine protein and CRE, and positively correlated with both lupus nephritis and C3 levels." (PMID 27965465, 2016). "Furthermore, we did comparisons of associations between renal injury indices and serum PTX3 level and other 2 conventional biomarkers, anti-ds-DNA antibody and C3 level, in lupus nephritis." (PMID 26817892, 2016). "Next, the diagnostic power for active lupus nephritis was analyzed by ROC curve analysis using the JKAP protein, C3, C4, and anti-dsDNA antibody levels of the SLE patients who may have nephritis." (PMID 27557500, 2016). "Considering the relationship between Dkk-1, C3 and anti-dsDNA antibody, our data suggested that Dkk-1 might play a protective role in lupus nephritis." (PMID 24465439, 2014). "In addition, our patient had other risk factors of ESRD associated with lupus nephritis such as race (nonwhite), eGFR at baseline (36.6 mL/min/1.73 m2), hypocomplementaemia (C3 26 mg/l, C4 4 mg/l, and CH50 < 14 U/mL) and renal histology (class IV)." (PMID 39918729, 2025). "Negative prognostic factors for lupus nephritis was associated with an initial Class IV histology (relative risk, 1.78), hypertension at presentation (relative risk, 1.67), and low C3 complement level in conjunction with a high creatinine level (relative risk, 1.52)." (PMID 39661284, 2025). "In the cohort with lupus nephritis (n = 32), drusen counts were higher in people aged >40 years (P < 0.045), with longer disease duration (P = 0.03), renal impairment (P = 0.02), or class IV nephritis (P = 0.03) and demonstrated a trend with C3 deposits (P = 0.098)." (PMID 35497809, 2022). "Also, the levels of IgG subclasses, C1q, and C3 deposition in lupus nephritis (LN) were detected." (PMID 27597802, 2016). "Thus, we further analyzed the correlation between JKAP levels in T cells and serum complement levels using lupus nephritis patients; JKAP protein levels in T cells were significantly correlated with serum C3 levels in lupus nephritis patients (r = 0.463, n = 21, P = 0.035)." (PMID 27557500, 2016). "Laboratory evaluation revealed positive antinuclear antibodies, anti-double-stranded DNA antibodies, hypocomplementemia (characterized by low levels of C3 and C4), and proteinuria, confirming the diagnosis of new-onset SLE with lupus nephritis." (PMID 41458657, 2025). "In this study, a difference of 2+ intensity between IF-FFPE and IF-Frozen was noted in two cases of lupus nephritis (IgM and C3), one case of IgA nephropathy (IgA), and one case of MPGN (IgA and C3)." (PMID 37503479, 2023).